PDSS2 (decaprenyl diphosphate synthase subunit 2)
Diseases named in the same sentence as PDSS2 in open-access papers (continued):
Sharing a sentence is not in itself a finding about the gene and the disease.
colon adenocarcinoma (1 paper, 2025). "This process yielded a four-gene signature—PDSS2, GRSF1, SLC39A8, and P4HA1—with significant prognostic value in colon adenocarcinoma." (PMID 40959429, 2025).
Hypercholesterolemia (1 paper, 2008). An increased concentration of cholesterol in the blood. "However, significantly elevated plasma cholesterol was also seen in B6.Alb/cre,Pdss2loxP/loxP (94 +/− 7.1 mg/dl) when compared with B6.Pdss2loxP/loxP controls (61 +/− 5.5 mg/dl), suggesting that a Pdss2 defect in the hepatocytes does contribute to hypercholesterolemia." (PMID 18437205, 2008).
Infertility (1 paper, 2015). "Oocyte-specific disruption of Pdss2 recapitulated many of the mitochondrial and reproductive phenotypes observed in the old females including reduced ATP production and increased meiotic spindle abnormalities, resulting in infertility." (PMID 26111777, 2015).
liver dysfunction (1 paper, 2024). "On the other hand, mice with liver-specific KO of Pdss2 (Alb-Cre;Pdss2 loxP/loxP) showed no overt manifestations of liver dysfunction, despite very low CoQ levels." (PMID 38722242, 2024).
lymph node metastasis (1 paper, 2014). "Decreased levels of PDSS2 mRNA in GCs were significantly associated with carbohydrate antigen (CA) 19-9 > 37 IU/ml and lymph node metastasis." (PMID 25330808, 2014). "Decreased PDSS2 mRNA expression in GCs was significantly associated with elevated preoperative CA19-9 levels and lymph node metastasis and was identified as an independent prognostic factor." (PMID 25330808, 2014).
premature ovarian failure (1 paper, 2015). "Ovarian reserve in the oocyte-specific Pdss2-deficient animals was diminished, leading to premature ovarian failure which could be prevented by maternal dietary administration of CoQ10." (PMID 26111777, 2015). "By 4 months of age, Pdss2 fl/fl Cre+ female ovaries contained no healthy follicles and were accompanied by a hypotrophic uterus, a condition resembling premature ovarian failure." (PMID 26111777, 2015).
primary coenzyme Q10 deficiency (1 paper, 2022). "LS is associated with genotypic heterogeneity, and it should be emphasized that in many genes related to the condition, PDSS2 gene, which is related to primary coenzyme Q10 deficiency, has also been described." (PMID 36295857, 2022).
primary coenzyme Q10 deficiency-3 (1 paper, 2023). "Disease-causing PDSS2 variants are also rare and are predominantly associated with nephropathology (primary coenzyme Q10 deficiency-3; COQ10D3; OMIM #614652)." (PMID 36978966, 2023).
steroid-resistant nephrotic syndrome (1 paper, 2018). Nephrotic syndrome, occurring in the pediatric population, in which proteinuria does not normalize with administration of steroids; this condition is unresponsive to a minimum of four weeks administration of oral corticosteroids. "Among the so far studied genes, 4: PDSS2/COQ1, COQ2, COQ6, and ADCK4/COQ8B are associated with steroid-resistant nephrotic syndrome (SRNS)—they are mutated in about 1% of cases." (PMID 30232548, 2018).
viral infection (1 paper, 2025). "In immune suppression aspect, enhancing coenzyme Q synthesis—by upregulating PDSS2—was found to boost mitochondrial respiration, facilitate the development of memory T cells after viral infection, and strengthen antitumor immune responses." (PMID 40959429, 2025).
tumor (11 papers, 2014 to 2025). "PDSS2 encodes a putative tumor suppressor, and we show here that its expression was regulated by hypermethylation of its promoter in GC cells." (PMID 25330808, 2014). "In addition, we found that different variants of PDSS2 exist in HCC tumor tissues and cell lines." (PMID 33064899, 2020). "In this research, we elucidate a novel molecular mechanism whereby PDSS2-Del2 enhances HCC tumor cell dissemination through its interaction with macrophages within the tumor microenvironment." (PMID 39695147, 2024). "Further research demonstrates that PDSS2-Del2 promotes HCC tumor cell metastasis not only by activating the tumor cell itself but also by interacting with immune cells in the tumor microenvironment." (PMID 39695147, 2024). "In our previous research, we identified PDSS2 (prenyl diphosphate synthase subunit 2) as a tumor suppressor gene in HCC." (PMID 39695147, 2024). "Our investigations revealed various splicing variants of PDSS2 within HCC cell lines and tumor tissues." (PMID 39695147, 2024). "To further investigate the relationship between PDSS2-Del2 expression and tumor progression, we evaluated the expression level of the second exon of PDSS2 in adjacent non-tumor tissues, tumor tissues and different stages of tumors." (PMID 39695147, 2024). "Lowered expression of PDSS2 enhances cancer cell proliferation and migration, and is closely correlated with reduced survival of cancer patients, implicating that PDSS2 will be a novel potential tumor suppressor gene 31, 33, 41-43." (PMID 36860919, 2023). "PDSS2 (prenyldiphosphate synthase subunit 2) was characterized as a tumor suppressor, and introduction of PDSS2 into cancer cells has been verified to inhibit tumor growth." (PMID 36185199, 2022). "Low PDSS2 expression has been reported in different tumor types, including NSCLC, where the role of this protein as a tumor suppressor has been described." (PMID 33802597, 2021). "Elevated PDSS2‐Del2 expression in HCC tumor cells decreased fumarate levels and activated the canonical NF‐κB pathway." (PMID 33064899, 2020). "The correlation study showed that PDSS2‐Del2 positive staining correlated with tumor stage (P = 0.008) and tumor embolus formation (P = 0.001)." (PMID 33064899, 2020). "The correlation analysis indicated that PDSS2‐Del2 expression correlated significantly with microvessel counts in HCC tumor tissues (R = 0.280, P = 0.007)." (PMID 33064899, 2020). "It has been reported that PDSS2 is downregulated in several types of tumors and acts as a potential tumor suppressor gene to inhibit the proliferation and migration of cancer cells." (PMID 31783675, 2019). "Prenyl diphosphate synthase subunit 2 (PDSS2) was identified in 2005, and evidence indicates that it acts as a tumor suppressor." (PMID 25330808, 2014). "Here we show that PDSS2 mRNA was heterogeneously expressed in GC cell lines, and its expression was inhibited in 73% and 32% of GC cell lines and tumor tissues, respectively." (PMID 25330808, 2014). "Similarly, PDSS2 showed strong cytoplasmic/membranous staining in tumor tissues, whereas the staining in normal tissues was low and weak." (PMID 40959429, 2025). "Likewise, the tumor suppressive role of PDSS2 was further strengthened with findings of COAD presented in our study." (PMID 36185199, 2022). "Our previous study identified a novel alternative splicing variant of prenyl diphosphate synthase subunit 2 (PDSS2) in HCC characterized by a deletion of exon 2, named PDSS2‐Del2, which is devoid of the tumor‐suppressive function of full‐length PDSS2 (PDSS2‐FL)." (PMID 33064899, 2020). "PDSS2‐Del2 levels correlated significantly with microvessel counts in HCC tumor tissues." (PMID 33064899, 2020). "PDSS2‐Del2 positive staining was correlated with tumor stage and tumor embolus formation." (PMID 33064899, 2020). "Furthermore, we discovered that elevated PDSS2‐Del2 expression in HCC tumor cells decreased fumarate levels and activated the canonical nuclear factor‐κB pathway." (PMID 33064899, 2020).
tumor (continued). "Because fumarate decreased in PDSS2‐Del2 cells, we were wondering whether fumarate supplementation could inhibit tumor cell metastasis." (PMID 33064899, 2020). "PDSS2 resides within the chromosomal locus 6q16.3-21, a site of frequent microsatellite DNA instability and loss of heterozygosity (LOH) in GC, supporting its role as a tumor suppressor in gastric epithelial cells." (PMID 25330808, 2014). "This literature led us to wonder whether PDSS2‐Del2 could promote HCC tumor cell metastasis." (PMID 33064899, 2020). "Gain-of-function studies revealed that exogenous overexpression of PDSS2 prominently inhibits tumor cell growth and invasion, highly suggesting that PDSS2 might act as a novel potential tumor suppresser gene and serve as a potential therapeutic target for cancers." (PMID 31783675, 2019). "This tumor suppressive mechanism of PDSS2 might be applied to GC as well." (PMID 25330808, 2014). "Specifically, PDSS2, GRSF1, SLC39A8 and P4HA1 were significantly upregulated in tumor tissues compared to normal samples." (PMID 40959429, 2025). "Specifically, analysis of proteomic data from the Human Protein Atlas (HPA) revealed that PDSS2, GRSF1, SLC39A8, and P4HA1 are markedly upregulated in tumor tissues compared to normal samples." (PMID 40959429, 2025). "Overall, our study elucidates the molecular mechanism through which PDSS2-Del2 promotes HCC metastasis, potentially contributing to the development of effective clinical treatments for HCC and preventing tumor metastasis." (PMID 39695147, 2024). "Our previous studies have found that the new transcript of PDSS2, PDSS2-Del2, is highly expressed in HCC tumor tissues and is correlated with tumor metastasis." (PMID 39695147, 2024). "Taken together, these results demonstrate that the overexpression of PDSS2-Del2 in HCC cells enhances MST1 secretion by expediting SKOR1 degradation, subsequently recruiting macrophages into the tumor microenvironment." (PMID 39695147, 2024). "Our study elucidates a novel molecular mechanism by which PDSS2-Del2 promotes HCC metastasis, which may contribute to the development of effective HCC clinical treatment and prevent tumor metastasis." (PMID 39695147, 2024). "The ratio of PDSS2‐Del2/FL was significantly increased in HCC tumor tissues compared with nontumor tissues (P = 0.0185)." (PMID 33064899, 2020). "Unlike full‐length PDSS2, which has a tumor‐suppressive function, PDSS2‐Del2 promoted HCC metastasis and angiogenesis." (PMID 33064899, 2020). "This study was limited by its lack of sufficient functional analysis of PDSS2, which tempers the conclusion that it acts as a tumor suppressor in GC." (PMID 25330808, 2014). "Prenyl diphosphate synthase subunit 2 (PDSS2) is required for coenzyme Q10 biosynthesis and acts as a tumor suppressor; however, the role and regulatory mechanisms of PDSS2 in GC are not understood." (PMID 25330808, 2014). "Co-culturing with PDSS2-Del2 overexpressed HCC cells stimulates the PI3K/AKT signaling pathway in macrophages, promotes macrophage differentiation towards the M2 type, and induces MMP2/MMP9 secretion, thereby providing a suitable microenvironment for tumor metastasis." (PMID 39695147, 2024). "The tumor‐suppressive function of PDSS2 was absent in PDSS2‐Del2‐overexpressing cells." (PMID 33064899, 2020). "Here, we found that PDSS2‐Del2 could increase HCC cell motility and tumor metastasis." (PMID 33064899, 2020). "Positive staining for PDSS2‐Del2 was detected in 5.31% (6/113) of nontumor tissues, whereas the positive staining increased to 24.56% (28/114) in HCC tumor tissues (P < 0.01)." (PMID 33064899, 2020). "We detected PDSS2‐Del2 and PDSS2‐FL in 128 pairs of HCC tumor tissues and their corresponding nontumor tissues with qPCR." (PMID 33064899, 2020).
kidney disease (9 papers, 2008 to 2024). "The effect of CoQ deficiency on oxidative stress has also been examined in the kidney of Pdss2kd/kd mice harboring a homozygous kidney disease (kd) mutation in Pdss2." (PMID 38722242, 2024). "A positional cloning approach demonstrated that the kd allele is a missense mutation in Pdss2 gene (Pdss2kd/kd), showing that the failure in the coenzyme Q biosynthetic pathway is the cause of a lethal kidney disease in mice." (PMID 34829558, 2021). "Similar kidney disease was seen in mice carrying PDSS2 missense mutations and in glomerular podocytes conditional PDSS2 knockout mice, but not in renal tubular epithelium, monocytes, or hepatocytes conditional knockout mice." (PMID 25166907, 2014). "Here, we show that the failure to make Coenzyme Q due to a Pdss2 mutation is the cause of a lethal kidney disease in mice that was previously thought to result from an autoimmune process." (PMID 18437205, 2008). "A mutation in Pdss2 was reported in mice with inherited kidney disease." (PMID 34829558, 2021). "All of the results indicated that the tissue-specific PDSS2 dysfunction associated with CoQ deficiency might be responsible for the renal disease phenotype." (PMID 25166907, 2014). "This work demonstrates that renal disease in Pdss2kd/kd mice results from podocyte-specific Pdss2 dysfunction." (PMID 18437205, 2008). "Although no proven effective treatment for the renal disease seen in mitochondrial disease exists, there are encouraging findings for some specific mitochondrial conditions such as PDSS2‐associated CoQ10 deficiency where administration of CoQ10 was found to have beneficial effects in affected mice." (PMID 31568715, 2019). "Although its identity was not understood at the time, the first known mutation in the Pdss2 gene arose spontaneously in the CBA/CaH colony of Dr. Mary Lyon and was designated kidney disease (kd)." (PMID 18437205, 2008).
cancer (5 papers, 2014 to 2023). A tumor composed of atypical neoplastic, often pleomorphic cells that invade other tissues. "Our findings regarding PDSS2 were opposite to the findings of decreased PDSS2 protein level reported by other groups for several cancer tissues." (PMID 35204836, 2022). "Up to now, all the reports regarding the role of PDSS2 in cancers focus on its expression profiling and functional analysis." (PMID 31783675, 2019). "In addition, many studies have conducted IHC to detect PDSS2 in cancer tissues, meaning that the results have been relatively nonquantitative; the IHC signals could have been from nonspecific proteins." (PMID 35204836, 2022). "Therefore, we deduced that Sp1 might recruit DNMT1 to promote DNA methylation in the PDSS2 promoter region, resulting in repressed expression of PDSS2 transcription in cancer cells." (PMID 31783675, 2019).
metabolism disorders (1 paper, 2023). "The study confirmed that CoQ deficiency caused by Pdss2 enzyme defects in podocytes leads to polyunsaturated fatty acid (PUFA) metabolism disorders and Braf/Mapk pathway disorders but not ETC., dysfunction." (PMID 38161691, 2023).
PDSS2 also shares sentences with these, for which no sentence is quoted: malignant melanoma (4 papers); hypertrophic cardiomyopathy (3); cerebellar ataxia (2); encephalomyopathy (2); lactic acidosis (2); mitochondrial disease (2); Progressive encephalopathy (2); cardiomyopathy (1); cerebral palsy (1); cognitive decline (1); cortical blindness (1); deafness (1); Encephalopathy (1); end-stage renal disease (1); glomerulopathy (1); heart defects (1); liver cancer (1); lung adenocarcinoma (1); MELAS (1); Mitochondrial myopathy (1); myopathy (1); neuromuscular disease (1); non-small cell lung carcinoma (1); retinitis pigmentosa (1); Seizure (1); triple-negative breast carcinoma (1).